CDS1 (CDP-diacylglycerol synthase 1)
Description:
Catalyzes the conversion of phosphatidic acid (PA) to CDP-diacylglycerol (CDP-DAG), an essential intermediate in the synthesis of phosphatidylglycerol, cardiolipin and phosphatidylinositol. Exhibits almost no acyl chain preference for PA, showing no discrimination for the sn-1/sn-2 acyl chain composition of PAs. Plays an important role in regulating the growth of lipid droplets which are storage organelles at the center of lipid and energy homeostasis. Positively regulates the differentiation and development of adipocytes (By similarity).
Synonyms: CDS 1
Tractability: Antibody: UniProt predicts a signal peptide or a membrane-spanning region. PROTAC: ubiquitination databases record sites on it; its protein half-life has been measured.
Gene: Protein-coding gene on chromosome 4 (84,582,879 to 84,651,334, forward strand). Ensembl gene ENSG00000163624.
Subcellular location: Endoplasmic reticulum membrane
Pathways (Reactome):
Metabolism: Synthesis of PI
Gene Ontology:
Molecular function: phosphatidate cytidylyltransferase activity; protein binding; diacylglycerol cholinephosphotransferase activity; transferase activity, transferring phosphorus-containing groups
Biological process: CDP-diacylglycerol biosynthetic process; lipid droplet formation; phosphatidylinositol biosynthetic process; phototransduction; positive regulation of fat cell differentiation; signal transduction
Cellular component: endoplasmic reticulum; endoplasmic reticulum membrane; membrane
Genetic constraint (gnomAD): Loss-of-function variants: 11 observed, 18.86 expected, observed/expected ratio (o/e) 0.58, 90% interval 0.37 to 0.96. The upper end of that interval is the gene's LOEUF score, 0.96, which puts it in group 4 of 6, group 1 being the genes least tolerant of losing a copy. Missense variants: 168 observed, 187 expected, observed/expected ratio (o/e) 0.9, 90% interval 0.79 to 1.02. Synonymous variants: 85 observed, 76.19 expected, observed/expected ratio (o/e) 1.12, 90% interval 0.94 to 1.34.
Homologues: Orthologues: chimpanzee CDS1 (99% identical), macaque CDS1 (99% identical), dog CDS1 (97% identical), rabbit CDS1 (96% identical), pig CDS1 (96% identical), mouse Cds1 (96% identical), rat Cds1 (95% identical), guinea pig CDS1 (87% identical), zebrafish cds1 (76% identical), tropical clawed frog cds1 (74% identical), Drosophila melanogaster Cds (56% identical), Caenorhabditis elegans cdgs-1 (51% identical). Paralogues in human: CDS2 (69% identical).
Diseases named in the same sentence as CDS1 in open-access papers:
CDS1 is named in the same sentence as 12 diseases in open-access papers, as found by Europe PMC text mining. Sharing a sentence is not in itself a finding about the gene and the disease. The quoted sentences say what the papers report.
heart failure (1 paper, 2018). Inability of the heart to pump blood at an adequate rate to meet tissue metabolic requirements. "CDS1 has been shown to be highly expressed in the heart and in SHHF (spontaneously hypertensive heart failure) rats, an increase in CDS1 mRNA was observed with increasing age whilst CDS2 mRNA decreased during heart failure development." (PMID 29253589, 2018).
prostatic disease (1 paper, 2025). "Additional contributors to prostatic disease progression include ALDH2 and CDS1, which are implicated in glycerophospholipid-related pathways." (PMID 40626307, 2025).
retinal degeneration (1 paper, 2016). Degeneration of the retina. "Drosophila PI synthase (dPIS) produces PI from CDP-DAG, and its overexpression partially suppresses the retinal degeneration phenotype in the eye of the cds1 mutant." (PMID 26791243, 2016).
skin cancer (1 paper, 2025). "We also observed that lung, blood, brain and skin cancers have reduced CDS1 levels compared with their lineages of origin, suggesting that these cancers may suppress transcription of CDS1 during cancer development." (PMID 40615674, 2025).
uveal melanoma (1 paper, 2025). A melanoma derived from melanocytes of the uveal tract. "Among our 76 uveal melanoma-specific essential genes and 105 synthetic lethal gene pairs, we identified and validated the CDP-diacylglycerol synthase 2 gene (CDS2) as a genetic dependency in the context of low CDP-diacylglycerol synthase 1 gene (CDS1) expression." (PMID 40615675, 2025).
cancer (6 papers, 2017 to 2025). A tumor composed of atypical neoplastic, often pleomorphic cells that invade other tissues. "This is in line with our data linking low CDS1 expression to mesenchymal-like cancers and the notion that roughly half of all cancers are mesenchymal like 59,60." (PMID 40615674, 2025). "An example is the mesenchymal transcription factor ZEB1, depletion of which induces CDS1, but also reduces cancer cell survival." (PMID 40615674, 2025). "Both results support the notion that ZEB1 suppresses CDS1 expression in mesenchymal-like cancers." (PMID 40615674, 2025). "In contrast, genes in neural (CDS1 and CHD4) and cancer-related (BTG1, COL6A1, PMP22 and HIF1A) pathways were increased by STAT3-KD, and their expression was reduced by STAT3 expression." (PMID 29774125, 2018). "Among other genes in the modules, SH2D3A, AP1M2, CDS1 and SCNN1A haven’t been previously studied in cancer biology." (PMID 28651527, 2017).
tumor (4 papers, 2016 to 2025). "By modulating lipid metabolism, CDS1 serves as a tumor suppressor, inhibiting NPC cell proliferation and metastasis." (PMID 40566856, 2025). "To investigate CDS1 gene expression in NPC, we conducted qRT-PCR analysis on the immortalized normal epithelial cell line NP460, and five tumor cell lines derived from primary NPC tumors (CNE1, HONE1, C666–1, HK1, and 5-8F)." (PMID 40566856, 2025). "Although CDS1 is thought to act as a tumor suppressor, there is no much information in this field." (PMID 32183400, 2020).
infection (2 papers, 2014 to 2025). The state of being infected such as from the introduction of a foreign agent such as serum, vaccine, antigenic substance or organism. "The infection was screened and confirmed by gyrB1 gene presence while detecting the cds1, pvsA, and qseC genes indicated virulence." (PMID 40908496, 2025).
CDS1 also shares sentences with these, for which no sentence is quoted: colorectal cancer (1 paper); lysosomal disorders (1); myopia (1); nasopharyngeal carcinoma (1).